EGFR (epidermal growth factor receptor)
Diseases named in the same sentence as EGFR in open-access papers (continued):
Sharing a sentence is not in itself a finding about the gene and the disease.
non-small cell lung carcinoma (continued). "In non-small cell lung carcinoma (NSCLC) cells, we observed that TRPC1 was involved in SOCE and that TRPC1 depletion altered EGFR activation and induced a G0/G1 cell cycle arrest resulting in a dramatic decrease in cell growth." (PMID 29662626, 2018). "EGFR, e.g., HER1, a protein, tyrosine-kinase receptors are surface receptors over-expressed in many solid tumors, such as colorectal cancer (CRC), non-small cell lung cancer (NSCLC), breast, ovary and prostate." (PMID 29315231, 2018). "Similar paradigms of second- and third-generation kinase inhibitors to tackle drug resistance mutations arising from first-generation inhibitors are also found in mutant EGFR and ALK-fusion positive non-small-cell lung cancer (NSCLC)." (PMID 30072489, 2018). "In the last decade, significant improvement in the treatment of several cancers (i.e., metastatic colorectal cancer, non-small cell lung cancer or head and neck SCC) has been obtained with the use of monoclonal anti-EGFR antibodies." (PMID 29700411, 2018). "Since oncogenic mutations and aberrant activation of EGFR occurs frequently in various tumor types including non-small cell lung carcinomas (NSCLC), SFK inhibitors are currently used to treat various malignancies." (PMID 30285892, 2018). "EGFR and HER2 double positive patients significantly increase recurrence rates compared with patients expressing EGFR or HER2 in non-small cell lung cancer." (PMID 28881584, 2017). "The oral EGFR tyrosine kinase inhibitor (TKI), erlotinib, is approved by the FDA depending on extend overall survival (OS) in previously treated non-small-cell lung cancer." (PMID 27690345, 2017). "Accumulating evidence supports a role for STAT proteins also in resistance to EGFR inhibitors in several preclinical models, including glioma, head and neck squamous cell carcinoma (HNSCC), and non-small cell lung cancer (NSCLC)." (PMID 28002810, 2017). "Epidermal growth factor receptor (EGFR) and KRAS gene are important driver genes of non-small cell lung cancer (NSCLC)." (PMID 28935015, 2017). "Erlotinib, an orally active tyrosine kinase inhibitor (TKI) of EGFR, is currently FDA approved for use in non-small cell lung cancer, as well as in pancreatic cancer when administered in combination with gemcitabine." (PMID 27853997, 2017). "In gefitinib-resistant non-small-cell lung cancer, IL-6R/JAK1/STAT3 signaling activation leads to de novo resistance to irreversible EGFR inhibitors." (PMID 27861147, 2017). "Here we demonstrate that in non-small cell lung carcinoma (NSCLC) cells, A549 and GLC82, PGE2 promotes nuclear translocation of epidermal growth factor receptor (nEGFR), affects gene expression and induces cell growth." (PMID 28415726, 2017). "Genes down-regulated in H1975 cells (non-small cell lung cancer, NSCLC) resistant to gefitinib [PubChem=123631] after treatment with EGFR inhibitor CL-387785 [PubChem=2776] for 24h." (PMID 28423528, 2017). "Cetuximab is considered as a promising therapeutic agent in EGFR overexpressed and/or abnormally activated tumors including HNSCC, metastatic colorectal cancer and non-small cell lung cancer." (PMID 29190900, 2017). "Around 80% of lung cancers are non-small-cell lung cancers (NSCLC), whose management remains challenging despite recent advances based on tumor genetic stratification using relevant biomarkers, such as EGFR, ALK, ROS-1, MET and KRAS2." (PMID 28860486, 2017). "Comparably to HER2, anti-EGFR antibodies and small molecule inhibitors are approved for clinical use for colorectal, head and neck squamous cell carcinomas (HNSCC) and non-small cell lung cancer." (PMID 27683128, 2017). "Gefitinib, an epidermal growth factor receptor (EGFR) tyrosine kinase inhibitor, is used as a first-line treatment for advanced non-small cell lung cancer (NSCLC)." (PMID 28592790, 2017).
non-small cell lung carcinoma (continued). "In non-small cell lung cancer (NSCLC), several reports have also shown that EGFR-specific tyrosine kinase inhibitors, such as gefitinib and erlotinib, are capable of reducing brain and adrenal metastases." (PMID 28854970, 2017). "Activating mutations of the EGFR are frequently found in the EGFR TKI responder in non-small cell lung carcinoma (NSCLC) patients, the majority of which are “never smoker” Asian women." (PMID 28134774, 2017). "In particular, one study shows that upregulation of the Hippo/YAP pathway in non-small cell lung cancer (NSCLC) cells induces AXL expression and leads to increased resistance to inhibition of the epidermal growth factor receptor (EGFR)." (PMID 28251492, 2017). "Discordance of mutational status in primary and metastatic lesions has been shown to be as high as 28% and 24% in EGFR and KRAS, respectively, in a cohort of 25 patients with stage IV non-small-cell lung cancers (NSCLC)." (PMID 28392802, 2017). "It exhibits potent inhibition on A549 non-small cell lung cancer (NSCLC) cell xenograft growth, and overcomes the resistance of xenograft to EGFR inhibitor gefitinib." (PMID 28592260, 2017). "Our previous work identified a 13-gene miRNA signature predictive of response to the epidermal growth factor receptor (EGFR) inhibitor, erlotinib, in Non-Small Cell Lung Cancer cell lines." (PMID 28646226, 2017). "Newly approved drugs targeting epidermal growth factor receptor (EGFR) and poly ADP-ribose polymerase 1 (PARP1) improved the clinical outcomes of non-small cell lung cancer and ovarian cancer patients." (PMID 28947756, 2017). "It showed potent EGFR signaling inhibition in experimental models, including first-generation TKI-resistant non-small cell lung cancer (NSCLC) cell lines." (PMID 28424775, 2017). "Good examples include the use of mTor inhibitors in renal cell carcinomas, epidermal growth factor receptor (EGFR) and PDL1 inhibitors in non-small cell lung carcinoma and the experimental use of insulin growth factor-1 receptor (IGF1R) inhibitors in sarcomas." (PMID 27509178, 2016). "In fact, acquired resistance to gefitinib, an EGFR tyrosine kinase inhibitor, can be mediated by MET amplification in patients with non-small cell lung cancer (NSCLC)." (PMID 27055285, 2016). "Non-small cell lung cancers (NSCLC) and head-and-neck cancers also show overexpression of EGFR and EGFR ligands in more than half of tumor samples." (PMID 27153091, 2016). "Gefitinib, an EGFR tyrosine kinase inhibitor, is used as FDA approved drug in breast cancer and non-small cell lung cancer treatment." (PMID 27653775, 2016). "Icotinib is a new epidermal growth factor receptor (EGFR) tyrosine kinase inhibitor (TKI) that developed and used in China; this work was to evaluate its efficacy and safety in treating non-small cell lung cancer (NSCLC)." (PMID 27893423, 2016). "Epidermal growth factor receptor (EGFR) tyrosine kinase inhibitors (TKI), such as gefitinib, have been demonstrated to effectively treat the patients of extracranial non-small cell lung cancer (NSCLC)." (PMID 27916828, 2016). "It has been proven that epidermal growth factor receptor (EGFR), anaplastic lymphoma kinase (ALK), and KRAS are common driver genes in non-small cell lung cancer (NSCLC)." (PMID 27760592, 2016). "Gefitinib, an EGFR-TKI, was previously shown to be effective in the treatment of brain metastases from non-small cell lung cancer (NSCLC) by overcoming the BBB." (PMID 26724810, 2016). "We have recently demonstrated for non-small cell lung carcinoma (NSCLC) cell lines, that EGFR inhibition by the small molecule inhibitor erlotinib induces a cell cycle arrest in G1." (PMID 27281611, 2016). "The most widely studied of these is the epidermal growth factor receptor (EGFR), with the small-molecule inhibitor gefitinib being the first quinazoline derivative to be approved for the treatment of Non-Small Cell Lung Cancer." (PMID 26861266, 2016).
non-small cell lung carcinoma (continued). "In recent years, targeted drugs occupy a pivotal position in the treatment of non-small cell lung cancer (NSCLC), drugs targeting epidermal growth factor receptor (EGFR) has been widely used in clinical practice, it is of milestone significance." (PMID 27760604, 2016). "EGFR, KRAS, and ALK alterations are major genetic changes found in non-small cell lung cancers (NSCLCs)." (PMID 26992209, 2016). "Epidermal growth factor receptor (EGFR), and anaplastic lymphoma kinase (ALK), are important oncogenic drivers in non-small-cell lung cancer (NSCLC), and other oncogenic drivers in NSCLC, such as ROS1 and KRAS, have also been found." (PMID 27533086, 2016). "We found that the Hh signaling pathway was silenced in EGFR-TKI-sensitive non-small-cell lung cancer (NSCLC) cells, while it was inappropriately activated in EGFR-TKI-resistant NSCLC cells, accompanied by EMT induction and ABCG2 overexpression." (PMID 26943330, 2016). "In conclusion, the genetic mutations associated with PACC are different from those implicated in non-small cell lung cancer, and EGFR, KRAS, BRAF, ALK, PIK3CA, PDGFRA, and DDR2 may not be driver genes in PACC; we must identify other genes for targeted therapy against PACC." (PMID 26373952, 2015). "In contrast, both EGFR and HER2 expression has been found in patients with non-small-cell lung cancer with poor prognosis, erlotinib was beneficial in those patients in an EGFR-dependent way." (PMID 26673416, 2015). "Thus, drugs that target EGFR (cetuximab, erlotinib, and gefitinib) in combination with radiotherapy have been proven to be effective for treating certain solid tumors, such as head and neck cancer, non-small cell lung cancer, and rectal cancer with a favorable toxicity profile." (PMID 26392415, 2015). "Overexpressed miR-21 contributes to the resistance of HCC cells to interferon-α/5-fluorouracil, the acquired resistance of EGFR-TKI and gefitinib resistance in non-small cell lung cancer cells, and the acquired resistance to trastuzumab in breast cancer." (PMID 26311740, 2015). "Clinically, anti-EGFR monoclonal antibody and EGFR tyrosine kinase inhibitor (TKI) have already led to great success in head and neck, colorectal, and non-small cell lung cancers." (PMID 25980579, 2015). "Here, we show that non-small cell lung cancer cell lines harboring differing isoforms of mutant KRAS, can be broadly divided into EGFR/HER dependent and EGFR/HER independent groups." (PMID 25992771, 2015). "We identify the potential genes involved in EGFR TKI (tyrosine kinase inhibitor) resistance and study the therapeutic mechanism in the non-small cell lung cancers." (PMID 25871388, 2015). "Afatinib is known as a first-line FDA-approved drug for the treatment of metastatic non-small cell lung carcinoma (NSCLC) with EGFR mutations, which is a tyrosine kinase inhibitor (TKI) not only against EGFR mutations but also inhibit HER2-overexpressed breast cancer." (PMID 24947902, 2014). "The successes of targeted therapeutics against EGFR and ALK in non-small cell lung cancer (NSCLC) have demonstrated the substantial survival gains made possible by precision therapy." (PMID 25372020, 2014). "Unlike other tumor types such as non-small cell lung cancers (NSCLCs) or melanomas, in which target mutations are associated with massive regressions following treatment with specific inhibitors, genetic alterations of EGFR are extremely infrequent in colorectal tumors." (PMID 24811491, 2014). "A subset of patients with recurrent or metastatic non-small cell lung cancer (NSCLC) were treated with either erlotinib (n = 25), an EGFR inhibitor, or sorafenib (n = 37), a VEGFR inhibitor, in a second-line setting." (PMID 24580837, 2014). "Epidermal growth factor receptor (EGFR), a transmembrane glycoprotein, is frequently overexpressed in human tumors such as breast, ovarian, prostate, pancreatic, and non-small cell lung cancer (NSCLC)." (PMID 24722287, 2014).
non-small cell lung carcinoma (continued). "Gefitinib is a selective epidermal growth factor receptor-tyrosine kinase inhibitor (EGFR-TKI), which has come to be the most widely used in advanced non-small cell lung cancer (NSCLC) patients." (PMID 24527096, 2014). "Epidermal growth factor receptor (EGFR) inhibitors, for instance, are used in the treatment of colorectal cancer, head and neck cancer, non-small cell lung cancer, and pancreatic cancer among other malignancies and are in general well tolerated." (PMID 23918349, 2013). "In this study, we aimed to elucidate the relationship between ErbB1 gene copy number and EGFR expression in two cell lines derived from non small cell lung cancer." (PMID 23631593, 2013). "The first-generation EGFR inhibitors Gefitinib (IressaTM) and Erlotinib (TarcevaTM) were approved for non-small-cell lung cancer (NSCLC) therapy, and Lapatinib as a dual reversible EGFR/HER2 inhibitor was approved for breast cancer therapy." (PMID 23936329, 2013). "Epidermal growth factor receptor (EGFR) and vascular endothelial growth factor receptor 2 (VEGFR2) have emerged as two effective clinical targets for non-small-cell lung cancer (NSCLC)." (PMID 24124611, 2013). "Epidermal growth factor receptor (EGFR) and c-MET receptors are expressed on many non-small cell lung cancer (NSCLC) cells." (PMID 23527257, 2013). "HKI-272, also known as neratinib, is an oral, irreversible dual EGFR/HER2 inhibitor for breast and non-small-cell lung cancer." (PMID 23175565, 2013). "Epidermal growth factor receptor (EGFR) tyrosine kinase inhibitors (TKI), such as gefitinib, have been proven to efficiently inhibit the proliferation of a subset of non small-cell lung cancers (NSCLC)." (PMID 22815959, 2012). "Among transmembrane tyrosine kinases the EGF receptor (EGFR) is one of the main therapeutic targets since it is active in both colorectal (CRC) and non-small cell lung cancers (NSCLC)." (PMID 22558339, 2012). "Epidermal growth factor receptor (EGFR) dependency has been observed among several tumour types, including non-small-cell lung cancer (NSCLC), pancreatic ductal adenocarcinoma (PDAC), and colorectal cancers." (PMID 22045191, 2012). "To date, scientifically validated and widely accepted protocol and guidelines for detecting EGFR GCN, which have been available for non-small cell lung cancer, remain to be developed for mCRC." (PMID 22897982, 2012). "In Non Small Cell Lung Cancer (NSCLC), miR-128b functions as a tumor suppressor miRNA by controlling the production of EGFR." (PMID 23272654, 2012). "Erlotinib is used to treat non-small cell lung cancer and pancreatic cancer and is a RTK inhibitor targeting EGFR/HER1." (PMID 21982514, 2011). "For example, among non-small cell lung cancer (NSCLC) patients, 60% have been reported with EGFR overexpression and a poor prognosis (the median survival time is around 4-5 months)." (PMID 20828404, 2010). "Erlotinib, one of the epidermal growth factor receptor (EGFR) tyrosine kinase inhibitors (TKIs), is active and relatively well tolerated in chemotherapy-naïve elderly patients with advanced non-small cell lung cancer (NSCLC)." (PMID 21194444, 2010). "The development and clinical application of Tyrosine Kinase Inhibitors (TKIs) targeting the Epidermal Growth Factor Receptor (EGFR), such as erlotinib and gefitinib, provide important insights for the treatment of non small cell lung cancer (NSCLC)." (PMID 19889201, 2009). "The epidermal growth factor receptor (EGFR), a member of the ErbB family, has been identified as therapeutic target for HNSCC and several other malignomas like colorectal adenocarcinomas and non-small cell lung cancer." (PMID 19828033, 2009). "Regarding other members of the HER family, in non-small cell lung cancer (NSCLC), synergy has been shown between HDIs and the HER1 (EGFR) tyrosine kinase inhibitors erlotinib and gefitinib." (PMID 18728657, 2008).
non-small cell lung carcinoma (continued). "The expression and activity of the epidermal growth factor receptor (EGFR) are determinants of radiosensitivity in several tumour types, including non-small cell lung cancer (NSCLC)." (PMID 18253126, 2008). "These include methylated MGMT and EGFR-TKI in glioblastoma, EGFR-TKI and ERCC1 in non-small cell lung cancer and pathologic complete response in breast cancer." (PMID 22275966, 2008). "This has led to EGFR-targeted agents, such as the EGFR tyrosine kinase inhibitor (EGFR-TKI) gefitinib (‘Iressa’), being developed for the treatment of non-small-cell lung cancer (NSCLC)." (PMID 15340376, 2004). "Notably, in non-small-cell lung cancer (NSCLC), NOX4 mediates resistance to EGFR-targeted tyrosine kinase inhibitor (TKI) therapy by enhancing IL-8 and PD-L1 expression, thus promoting immune evasion and therapeutic resistance." (PMID 41562694, 2026). "While surgical postponement is recommended for patients with resectable non-small cell lung cancer (NSCLC) and active COVID-19, safe and effective bridging therapies during the delay remain poorly defined, especially for epidermal growth factor receptor (EGFR)-mutant disease." (PMID 42131806, 2026). "Additionally, EVs derived from the serum of non-small cell lung cancer (NSCLC) patients exhibit elevated levels of NPM1 protein and EGFR mRNA, suggesting relevance for this transportation mechanism to NSCLC pathogenesis." (PMID 41632872, 2026). "Erlotinib is an epidermal growth factor receptor (EGFR) tyrosine kinase inhibitor, effective as treatment for advanced non-small cell lung cancer; however, no quality evidence of its benefit in leptomeningeal carcinomatosis has been reported." (PMID 42222409, 2026). "For solid tumors, dual-targeting of EGFR and cellular mesenchymal epithelial transition factor (c-MET) with a bispecific antibody, amivantamab, is approved for treatment of patients with non-small cell lung cancer (NSCLC) with an exon 20 insertion in the EGFR gene." (PMID 41552759, 2026). "The effect of the EGFR-tyrosine kinase inhibitor, gefitinib, at suboptimal doses was reported to be potentiated in the presence of SREBP1 inhibitors such as betulin and fatostatin in models of non-small cell lung cancer." (PMID 40427160, 2025). "Non-small cell lung cancer (NSCLC) and EGFR/ALK inhibitors affect patients with NSCLC (those with adenocarcinoma and who are not smokers) who have mutations in the EGFR genes or rearrangements in the ALK gene." (PMID 40647400, 2025). "It acts on several key targets—epidermal growth factor receptor (EGFR), vascular endothelial growth factor receptor (VEGFR), and rearranged during transfection (RET) tyrosine kinase—and is used clinically in oncology, including non-small-cell lung carcinoma." (PMID 41011168, 2025). "Among all non-small cell lung cancers, the number of samples/cases with normal EGFR was 6006/5997, the number of samples/cases with abnormal EGFR was 1570/1425, and 83 cases had crossover and were not counted in the analysis." (PMID 40732366, 2025). "This study evaluates the financial impacts of expanding global access to PD1/PD-L1 inhibitors as first-line monotherapy for patients aged 40–74 years with advanced unresectable non-small cell lung cancer (NSCLC), with wildtype EGFR and ≥50% of tumour cells with PD-L1 expression." (PMID 40510923, 2025). "Moreover, experimental studies indicate that the MEOX2 and GLI-1 transcription factors can influence the genetic expression of EGFR, a key driver gene of non-small cell lung carcinomas (NSCLC), by modulating specific histone marks on its enhancer and promoter sequences." (PMID 39971779, 2025).